MIR1184-1 (microRNA 1184-1)
Synonyms: hsa-mir-1184; MIR1184; MIRN1184; hsa-mir-1184-1
Gene: MicroRNA gene on chromosome X (154,887,360 to 154,887,458, reverse strand). Ensembl gene ENSG00000221533.
Homologues: Orthologues: chimpanzee ptr-mir-1184-1 (100% identical). Paralogues in human: MIR1184-2 (100% identical), MIR1184-3 (100% identical).